VEGFA (vascular endothelial growth factor A)
Diseases named in the same sentence as VEGFA in open-access papers (continued):
Sharing a sentence is not in itself a finding about the gene and the disease.
age-related macular degeneration (646 papers, 2005 to 2026). Age-related loss of vision in the central portion of the retina (macula), secondary to retinal degeneration. "In ophthalmology, RfxCas13d has been used to target VEGFA, a gene associated with choroidal neovascularization in age-related macular degeneration." (PMID 39228750, 2024). "This cluster also shows a specific line of research into “anti- vascular endothelial growth factor A” as a strategy to limit the angiogenesis associated with the use of drugs like bevacizumab, for treating both different cancers and age-related macular degeneration." (PMID 33882849, 2021). "Neovascular age-related macular degeneration (AMD), a major cause of blindness driven by aberrant ocular neovascularization, has limited efficacy with current VEGFA-targeting therapies." (PMID 41010531, 2025). "VEGFA was demonstrated to be involved in age-related macular degeneration (AMD), a leading cause of visual impairment in aging populations." (PMID 33232279, 2020). "In the present work, the aim was to systematically review all studies about the association of vascular endothelial growth factor A (VEGF-A) polymorphisms with age-related macular degeneration (AMD) and to perform a meta-analysis." (PMID 23761723, 2013). "By reducing VEGFA expression, this strategy has the potential to mitigate the progression of age-related macular degeneration." (PMID 39228750, 2024). "Vascular endothelial growth factor-A (VEGF) is the angiogenic factor promoting the pathological neovascularization in age-related macular degeneration (AMD) or diabetic macular edema (DME)." (PMID 32710087, 2020). "It has been reported that VEGFA is related to type-2 diabetes, coronary artery disease, age-related macular degeneration and body fat." (PMID 25464127, 2014). "An example of this activation is the design of siRNAs against vascular endothelial growth factor-A as a treatment for age-related macular degeneration." (PMID 21747939, 2011). "Finally, faricimab, an antibody against vascular endothelial growth factor A and, in addition, angiopoietin-2, is a new option for the treatment of age-related macular degeneration." (PMID 37278927, 2023). "VEGFA overexpression and altered regulation of VEGFA signaling pathways lead to pathological angiogenesis, which contributes to the progression of various diseases, such as age-related macular degeneration and cancer." (PMID 34575413, 2021). "Age-related macular degeneration (AMD) is the most prevalent cause of blindness in the elderly, and its exsudative subtype critically depends on local production of vascular endothelial growth factor A (VEGF)." (PMID 24714223, 2014). "Intraocular anti-VEGFA injections are frequently used to counteract neovascularization in diseases such as the neovascular form of age-related macular degeneration (AMD)." (PMID 42276988, 2026). "SPHINX has been tested in vivo in the context of age-related macular degeneration (AMD), where it convincingly reduces choroidal neovascularization in rodents by promoting the expression of the anti-angiogenic VEGFA splice isoform." (PMID 36895328, 2023). "Bevacizumab (Avastin®), a full-length mAb against VEGFA, initially approved for the treatment of advanced carcinomas, has been used extensively also for age-related macular degeneration (AMD) and other chorioretinal vascular disorders." (PMID 34575413, 2021). "Vascular endothelial growth factor A (VEGFA) is involved in the pathogenesis of vasoproliferative retinal diseases, such as exudative age-related macular degeneration (AMD)." (PMID 30825671, 2019). "The cluster on neoplasms also includes an important line of research on anti-vascular endothelial growth factor A (anti-VEGF) treatments, both for different cancers and for age-related macular degeneration." (PMID 33882849, 2021). "VEGFA and VEGFR-neutralizing drugs are approved for use as anti-angiogenic agent in certain cancers and age-related macular degeneration." (PMID 32629875, 2020).
age-related macular degeneration (continued). "Recently, two humanized monoclonal antibodies targeting vascular endothelial growth factor-A (VEGF-A), ranibizumab (Lucentis) and bevacizumab (Avastin) have revolutionized the treatment of eye diseases such as age-related macular degeneration." (PMID 22229035, 2012).
gastric cancer (599 papers, 1996 to 2026). A primary or metastatic malignant neoplasm involving the stomach. "A previous study indicated that PVT1 was linked to the activation of STAT3/VEGFA signaling and promoted angiogenesis in patients with gastric cancer." (PMID 34336125, 2021). "The haplotype association analyses revealed that CTC haplotype of VEGFA gene (block three) was associated with gastric cancer susceptibility (p = 0.006), being more frequent in case (37.6%) than in control individuals (28.6%)." (PMID 30551681, 2018). "We detected that the A allele of rs699947 (VEGFA) was associated with a protection for developing gastric cancer in the Genotype, Dominant, and Allele Models when considering the total samples of cases, but not stratified for the diffuse subtype." (PMID 30551681, 2018). "Interestingly, in gastric cancer patients high VEGFA levels have been associated with reduced survival and increased tumor aggressiveness." (PMID 31263680, 2019). "Furthermore, A allele of rs699947 (VEGFA) was detected as a protection factor for developing gastric cancer in the Genotype, Dominant and Allele Models only when considering the total sample of cases (N = 178)." (PMID 30551681, 2018). "However, reinforcing the idea that haplotype studies are usually more informative than studying individual SNPs, we found that three different haplotypes of VEGFA (which include rs699947, rs833061, and rs2010963 polymorphisms) were associated with gastric cancer." (PMID 30551681, 2018). "In hepatocellular carcinoma, gastric cancer, and bladder cancer, miR-205-5p has been identified as a key regulator of angiogenesis through VEGFA modulation." (PMID 40002404, 2025). "Collectively, these results suggest that NAT10 promotes VEGFA expression and angiogenesis in gastric cancer by acetylating the lncRNA XIST." (PMID 40860183, 2025). "Through network analysis, AKT1, MAPK1, CDK2, PIK3CA, and VEGFA were found to be the key targets of HDW in the treatment of gastric cancer." (PMID 39086391, 2024). "The other approach to treating advanced gastric cancer is adoptive cell therapy, antibodies against vascular endothelial growth factor A (VEGFA), cancer vaccines, and chimeric antigen receptor (CAR) T-cell therapy." (PMID 39409942, 2024). "For example, circRANGAP1 regulates VEGFA expression by targeting miR-877-3p to facilitate gastric cancer invasion and metastasis." (PMID 38082189, 2024). "Up to now, only one study indicated that CREB3L4 involved in the tumor progression in gastric cancer via modulating VEGFA expression." (PMID 38303702, 2024). "The activation of the STAT3/VEGFA signaling axis by lncRNA PVT1 has been found to enhance angiogenesis in gastric cancer." (PMID 37915049, 2023). "The positive correlation between VEGFA expression and gastric cancer was verified, and a high level of VEGFA frequently predicted shorter survival time." (PMID 36834821, 2023). "Vascular endothelial growth factor A (VEGFA) play essential roles in the development of gastric cancer via its involvement in the formation of new blood vessels, a process termed as angiogenesis." (PMID 35844558, 2022). "As a tumor suppressor gene, lncRNA ZNF667-AS1 significantly hinders the propagation, metastasis, and angiogenesis of gastric cancer cells by promoting the expression of E-cadherin and inhibiting the expression of N-cadherin and VEGFA." (PMID 35813862, 2022). "For example, PVT1 stimulated angiogenesis by triggering the STAT3/VEGFA signaling pathways in gastric cancer." (PMID 35813862, 2022). "Previous studies have indicated that circ-RanGAP1 sponges miR-877-3p to modulate vascular endothelial growth factor A (VEGFA) expression, thus facilitating gastric cancer development." (PMID 35587154, 2022). "Clinical studies of combined therapies using VEGFA inhibitors and immune check point inhibitors among patients with advanced gastric cancer have shown promising effects, with enhanced anti-tumour effect and reduced toxicity." (PMID 35844558, 2022).
gastric cancer (continued). "This study shows that overexpression of lncRNA ZNF667-AS1 can significantly downregulate VEGFA in gastric cancer cells and constrain the angiogenesis ability of vascular endothelial cells." (PMID 35813862, 2022). "Hub genes containing COL5A2, JAG1, TIMP1, FGFR1, PDFGA, VEGFA, and PTK2 were collected from the gene sets and were proven to be linked to the occurrence and development of gastric cancer." (PMID 35875363, 2022). "Data showed that lncRNA ZNF667-AS1 upregulation significantly promoted the expression of E-cadherin in gastric cancer cells and inhibited the expression of N-cadherin and VEGFA." (PMID 35813862, 2022). "High expression of circ-RanGAP1 has a significant association with lymph node metastasis, advanced TNM stage, and worse survival in patients with gastric cancer and contributes to gastric cancer progression dependent on the miR-877-3p/VEGFA pathway." (PMID 35813866, 2022). "Circ-RanGAP1 sponges miR-877-3p to raise VEGFA production and boosts gastric cancer invasion and metastasis." (PMID 35821230, 2022). "For example, circ-RanGAP1 regulates vascular endothelial growth factor A (VEGFA) expression through miR-877-3p so as to aggravate cell invasion and metastasis in gastric cancer." (PMID 35365168, 2022). "MiR-205-5p is downregulated in gastric cancer tissues, it suppresses proliferation and angiogenesis in gastric cancer by reducing the expression of VEGFA and FGF1." (PMID 34977016, 2021). "circ-RanGAP1 is elevated in plasma exosomes from gastric cancer patients and facilitates gastric cancer invasiveness by upregulating VEGFA expression." (PMID 34109113, 2021). "In gastric cancer, miR-877-3p exhibited low expression in gastric cancer tissues, and miR-877-3p suppressed gastric cancer metastasis via targeting VEGFA." (PMID 34254950, 2021). "used siRNA of VEGFA to treat gastric cancer and found that renal cancer cells cultured in vitro showed selective VEGFA, in the tumor model of nude mice, inhibiting tumor growth by reducing the expression of VEGFA in tumor cells." (PMID 33869051, 2021). "In a smaller study of gastric cancer patients (n = 35), the median VEGFA value was 660 pg/mL in ascites." (PMID 34198773, 2021). "Circ-RanGAP1 regulated vascular endothelial growth factor A (VEGFA) by targeting miR-877-3p, thereby promoting the metastasis and invasion of gastric cancer." (PMID 34249673, 2021). "Angiogenesis, manifested by upregulated HIF1A and VEGFA, is a part of the healing process of the gastric mucosa as well as a means of gastric cancer growth and dissemination." (PMID 32630408, 2020). "In vitro and xenograft mouse models were used to evaluate the impact of VEGFA/VEGFR1 on gastric cancer peritoneal metastasis." (PMID 33081836, 2020). "Many target mRNAs of miR-29a, including but not limited to VEGFA in gastric carcinoma and IGF-1 in cardiac endothelial cells, have been discovered." (PMID 32733638, 2020). "Several studies have shown that IL-6 enhances VEGFA levels in various cell cancer types including gastric carcinoma, osteosarcoma, and multiple myeloma." (PMID 32318345, 2020). "Calreticulin (CRT) and vascular endothelial growth factor-A (VEGF-A) are crucial for angiogenesis, and mediate multiple malignant behaviors in gastric cancer." (PMID 31725767, 2019). "In particular, a positive correlation between CRT and Vascular endothelial growth factor-A (VEGF-A) has also been addressed in neuroblastoma, bladder cancer, and gastric cancer cell lines." (PMID 31725767, 2019). "Under hypoxic conditions, the expression of AM, HIF-1α, NDRG3, and VEGFA are significantly elevated in the human gastric cancer cell line BGC-823." (PMID 29179449, 2017). "Down-regulation of miR-126 was found to inversely correlate with an increased microvessel density (MVD) and vascular endothelial growth factor A (VEGF-A) expression in gastric cancer tissues." (PMID 25428912, 2014).
gastric cancer (continued). "In summary, our study uncovered that NAT10-mediated ac4C modification stabilizes lncRNA XIST, which recruits hnRNPK to facilitate YAP1 nuclear translocation and transcriptional activation, thereby driving VEGFA-dependent vascular abnormalization in gastric cancer." (PMID 40860183, 2025). "Moreover, CALM2 has been found to stimulate proliferation, migration, invasion, and angiogenesis of HUVECs, as well as M2 polarization of THP1 cells, through the JAK2/STAT3/HIF-1/VEGFA signaling pathway, thereby facilitating gastric cancer metastasis." (PMID 39695099, 2024). "Angiogenesis is also known to be a mechanism of the effect of PAI-1 on tumorigenesis via vascular endothelial growth factors, such as the activation of the VEGFR-2 signaling pathway in gastric cancer and paclitaxel resistance in triple-negative cancer via VEGFA." (PMID 38758826, 2024). "Many studies have shown an increase in the expression of the VEGFA gene in the tissues of various solid tumors, including gastric cancer, a positive correlation has been established between aberrant expression of the VEGFA gene and the presence of metastases and a poor prognosis of the disease." (PMID 36833207, 2023). "A recent study demonstrated that miR-877 may act as a tumor suppressor by suppressing vascular endothelial growth factor A (VEGFA) in gastric cancer." (PMID 34738872, 2022). "Furthermore, the experiment verified that the SJZD had a therapeutic effect on the gastric cancer model mice involving the VEGFA/PI3K/AKT pathways." (PMID 35463069, 2022). "The most widely applied immunotherapies against advanced gastric cancer including immune checkpoint inhibitors (ICIs), adoptive cell therapy, cancer vaccine, vascular endothelial growth factor A (VEGFA) antibody and chimeric antigen receptor (CAR) T therapy, etc." (PMID 35844558, 2022). "Silencing of AURKB may decrease the invasive and migratory capacities of gastric cancer cells by disrupting the VEGFA/Akt/mTOR and Wnt/-catenin/Myc pathways." (PMID 35354488, 2022). "Molecular mechanism studies displayed that the high level of lncRNA ZNF667-AS1 promoted the expression of E-cadherin and inhibited the expression of N-cadherin and VEGFA, leading to the inhibition of the proliferation, migration, and angiogenesis of gastric cancer cells." (PMID 35813862, 2022). "Furthermore, soluble proteins coded by the VEGFA gene were involved in the mechanism of inducing angiogenesis and immunosuppressive responses in gastric cancer." (PMID 34497663, 2021). "In addition, tumor inhibitory functions of miR-377-3p were demonstrated in pancreatic cancer by regulating a serine/threonine kinase, namely Pim-3 proto-oncogene, and in gastric cancer through reducing the level of vascular endothelial growth factor A (VEGFA)." (PMID 33817324, 2021). "Another study revealed that the axis of hypoxia–autophagy enhances the secretion of vascular endothelial growth factor A (VEGFA) from peritoneal mesothelial cells through mediating integrin α5-fibronectin signaling, which subsequently promotes the peritoneal metastasis in gastric cancer mouse model." (PMID 35355804, 2021). "miR-29a reduced the density of tumor microvessel in gastric cancer via targeting VEGFA." (PMID 34289832, 2021). "In addition, CAFs promote angiogenesis by producing fibroblast growth factor 2 (FGF2), and vascular endothelial growth factor A (VEGFA) in different cancers as well as galectin-1 expression in gastric cancer." (PMID 32264958, 2020).
gastric cancer (continued). "The anti-angiogenic drugs employed in gastric cancer clinical trials mainly target VEGFA such as the monoclonal humanized antibody bevacizumab, or the VEGFR2, in particular ramucirumab and selective tyrosine kinase inhibitors such as sunitinib, sorafenib and apatinib." (PMID 31263680, 2019). "Here, we unveil a previously unrecognized NAT10/XIST/YAP1/VEGFA signaling axis driving vascular abnormalization in gastric cancer (GC) and demonstrate its therapeutic potential in remodeling the tumor immune microenvironment." (PMID 40860183, 2025). "Thus, we hypothesized that XIST recruits hnRNPK to promote the nuclear translocation of the YAP1 protein and YAP1/TEAD4-mediated VEGFA transcription in gastric cancer cells." (PMID 40860183, 2025). "In addition, lncRNA PVT1 promotes angiogenesis via STAT3/VEGFA axis in gastric cancer." (PMID 32600379, 2020). "Additionally, re-expression of RUNX3 in gastric cells in a mouse model inhibited peritoneal metastasis and RUNX3 restoration in human gastric cancer cells suppressed vascular endothelial growth factor A (VEGF A) expression, leading to inhibition of angiogenesis, growth, and metastasis." (PMID 33298014, 2020). "Therefore, down-regulation of PDGFB and VEGFA may explain the anti-proliferative effect exerted by DACT1α in gastric cancer cells." (PMID 27833078, 2016). "For example, lncRNA PVT1 promotes angiogenesis by stabilizing STAT3, which then activates the STAT3/VEGFA signaling axis that drives upregulation of VEGF expression and tumor progression in gastric cancer—this is likely relevant to other cancers as well." (PMID 41154428, 2025). "In gastric cancer, FOXO1 also suppresses VEGFA and other angiogenesis‐related molecules, inhibiting vascular formation in the tumour area and enhancing immune responses against tumour cells." (PMID 38899748, 2024). "Four different human gastric cancer cell lines (HGC-27, NCI-N87 [N87], KATO III and AGS) were characterized by the expression of VEGFA and its receptor (VEGFR2) both at mRNA and protein level." (PMID 32346056, 2020). "The aims of this study were to investigate whether miR-4316 inhibited proliferation and migration by downregulating vascular endothelial growth factor A (VEGF-A) and its clinical significance in gastric cancer (GC)." (PMID 32123520, 2020). "Our qRT-PCR results showed the expression of AM, VEGFA, NDRG3, and HIF-1α allincreased, though to different degrees, and at different times, in the gastric cancer cell lines." (PMID 29179449, 2017). "In gastric cancer, NUTM2A-AS1 contributes to matrine resistance by forming a regulatory axis with miR-613 and VEGFA, where its knockdown decreases cell viability, reduces proliferation, and enhances apoptosis in tandem with altered ROS, glutathione levels, and superoxide dismutase activity." (PMID 40903777, 2025). "Key findings reveal that in gastric cancer, NUTM2A-AS1 functions as a ceRNA for miR‐376a, leading to upregulation of TET1 and HIF-1A and subsequent increase in PD-L1 expression, while also modulating matrine resistance via the miR‐613/ROS/VEGFA axis." (PMID 40903777, 2025). "The pro-metastatic role of TANs via lymphangiogenesis is nevertheless observed in multiple cancers—gastric cancer (CD15+ TANs correlate with nodal metastasis), bladder cancer (circDHTKD1/CXCL5/VEGFC axis; ETV4-CXCL1/8-MMP9/VEGFA axis), and now LUAD (CCL15-CCR1-VEGFC)." (PMID 40739091, 2025). "In addition, Calmodulin2 (CALM2) has been found to exhibit high expression in gastric cancer (GC) cells, modulating the JAK2/STAT3/HIF-1/VEGFA axis, promoting macrophage polarization, and facilitating ECs angiogenesis." (PMID 37666809, 2023).